NLRP3 (NLR family pyrin domain containing 3)
Diseases named in the same sentence as NLRP3 in open-access papers (continued):
Sharing a sentence is not in itself a finding about the gene and the disease.
osteoporosis (continued). "In addition, many studies reported that proinflammatory cytokines and their related genes such as galectin, NLRP3, and IL-6 have a significant pivotal role in the destruction of bones and severity of osteoporosis." (PMID 34938374, 2021). "As general, galectins as carbohydrate-binding proteins interfere in many physiological processes particularly inflammatory and immune response showed to be associated with activation of other proinflammatory markers such as NLRP3 inflammasome and aid in the progression of osteoporosis." (PMID 34938374, 2021). "Here, we briefly summarize recent studies on the mechanism of NLRP3 inflammasome in OP, provide information on new strategies for preventing and treating the disease, and investigate the ideal therapeutic target to treat osteoporosis." (PMID 34646239, 2021). "Melatonin’s introduction in osteoporosis can overturn the deleterious effects of NLRP3." (PMID 34202842, 2021). "Indeed, pyroptosis participates in the pathogenesis of osteoporosis mainly via activating NLRP3 and secreting mature IL-1β and IL-18, which will be demonstrated as follows." (PMID 33488513, 2020). "Additionally, NLRP3-deficient mice do not show a decrease in the bone marrow volume, indicating that the increased bone volumes in NLRP3-deficient mice are not caused by osteoporosis development due to osteoclast dysfunction." (PMID 35628185, 2022). "The nucleotide binding oligomerization domain, leucine-rich repeat and pyrin domain containing protein 3 (NLRP3) inflammasome is known as a cytosolic complex involved in producing proinflammatory cytokines consisting of interleukin- (IL-) 1β, which accelerates the occurrence of osteoporosis." (PMID 35872849, 2022). "Thus, this review highlights the recent studies on the function of NLRP3 inflammasome in osteoporosis, provides information on new strategies for managing osteoporosis, and investigates the ideal therapeutic target to treat osteoporosis." (PMID 34646239, 2021). "Furthermore, the NLRP3 inflammasome seems to be directly involved in osteoporosis." (PMID 32604771, 2020). "Melatonin inhibits the activation of NLRP3 inflammasome by mediating the Wnt/β-catenin pathway in BMSCs from ovariectomized (OVX) mice, thereby enhancing osteoporosis in OVX-treated mice." (PMID 33215255, 2021). "Our study suggests that NLRP3 could be a new target and INF 39 may be a potential option for prevention and treatment of osteoporosis." (PMID 35872849, 2022).
cerebral infarction (39 papers, 2016 to 2026). An ischemic condition of the brain, producing a persistent focal neurological deficit in the area of distribution of the cerebral arteries. "In vivo, combined therapy in the transient middle cerebral artery occlusion mouse model reduced cerebral infarction and improved neurological outcomes, accompanied by NLRP3/GSDMD downregulation and hippocampal neuron preservation." (PMID 40878776, 2026). "Calycosin significantly reduced neurological impairments and brain infarction in a dose-dependent manner, alleviated neuronal damage and decreased the expression of pyroptosis-related markers, including NLRP3, GSDMD, HMGB1, IL-1β, IL-18, and caspase-1." (PMID 40606597, 2025). "The results show that PGC-1α expression decreased and NLRP3 expression increased in I/R mice cerebral infarction region and Nef dramatically reversed PGC-1α and NLRP3 expression." (PMID 38910141, 2024). "NLRP3 inflammasomes are reliable markers for detecting post-cerebral infarction cell injury and key mediators for inflammatory response regulation." (PMID 37178321, 2023). "The decreased production of NLRP3 inhibits the activation of NLRP3 inflammatory bodies, thereby reducing the volume of cerebral infarction." (PMID 37636861, 2023). "Brain infarct volume, neurological deficits, NLRP3, microglia, and neuronal death were examined in sacrificed mice to explore the correction between NBP effects and NLRP3 expression." (PMID 36013423, 2022). "Geniposide has been shown to significantly reduce the area of cerebral infarction and alleviate neuronal damage and necrosis mainly by inhibiting inflammatory signals, including NLRP3, TNF-α, IL-6, and IL-1β." (PMID 34454545, 2021). "BTK inhibitors can inhibit the activation of NLRP3 inflammasome, reducing the volume of cerebral infarction, and improving the neurological impairment after I/R injury." (PMID 34526897, 2021). "MCC950, an NLRP3 inhibitor, can reduce the expression of NLRP3 in ischemic brain tissue, and we have discovered that an NLRP3 inhibitor can reduce neuronal apoptosis, cerebral infarct size, and neurological dysfunction." (PMID 34059091, 2021). "TGR5 activation by INT777 significantly decreased pro-inflammatory cytokine, cleaved caspase-8, and NLRP3 levels, thereby reducing brain infarctions; both short- and long-term neurobehavioral assessments showed improvements." (PMID 33531049, 2021). "MiR-17-5p mimic administration ameliorated TXNIP expression, NLRP3 inflammasome activation, caspase-1 cleavage, and IL-1β production, as well as brain infarct volume." (PMID 29394934, 2018). "Studies have shown that Genipin could significantly reduce the area of cerebral infarction and attenuate neuronal damage and necrosis by inhibiting inflammatory factors such as NLRP3, TNF-α, IL-6, and IL-1β." (PMID 39679371, 2024). "Compared with the model group, AST-IV significantly reduced the neurological function deficit score, cerebral infarct volume, and the protein levels of NLRP3, Caspase-1, pro-IL-1β, IL-1β, pro-IL-18, and IL-18 in brain tissue, and inhibited the expression of phosphorylated NF-κB protein." (PMID 38601463, 2024). "We found that LIPT1 was downregulated in cerebral infarction and negatively correlated with NLRP3." (PMID 36818726, 2022). "Thus, the pharmacological modulation of the NF-κB p65/NLRP3-mediated pathway and subsequent promotion of M1 to M2 polarization can reduce neurological deficits and cerebral infarct and is a promising therapeutic strategy in the acute stage of transient cerebral ischemia." (PMID 39391701, 2024). "Results showed that EA could reduce the score of neurological deficit, reduce the volume of cerebral infarction and improve the degree of nerve cell injury, and inhibit NLRP3, pro-caspase-1, cleaved caspase-1 p20, pro-IL-1β, cleaved IL-1β, and GSDMD protein expression." (PMID 35600074, 2022).
cerebral infarction (continued). "A study showed that acacetin could reduce the expression of NLRP3 and TNF-α to lessen ischemia-reperfusion injury after cerebral infarction." (PMID 38178669, 2024). "Both NADPH and Apocynin inhibit the expression of NLRP3, ASC, caspase-1, IL-1β, and IL-18 in the ischemic cerebral cortex in a rat cerebral infarction model, and reduce the volume of cerebral infarction, improve survival after infarction, and restore neurological function." (PMID 34526897, 2021). "Analyses revealed that Cel administration reduced brain infarction size, microglia activation, levels of inflammation factors, and levels of oxidative stress markers by upregulating levels of p-AMPKα, Nrf2, HO-1, and by downregulating levels of TXNIP and NLRP3." (PMID 38763946, 2024).
leukemia (39 papers, 2016 to 2026). A malignant (clonal) hematologic disorder, involving hematopoietic stem cells and characterized by the presence of primitive or atypical myeloid or lymphoid cells in the bone marrow and the blood. "The activation of NLRP3 in leukemia is associated with its pro-inflammatory phenotype, yet it seems to be decoupled from the induction of pyroptosis." (PMID 38730609, 2024). "Activation of the NLRP3 inflammasome has been associated with promoting proliferation, inhibiting apoptosis, and increasing drug resistance in primary leukemia cells." (PMID 39769450, 2024). "Further, recent studies also indicate that NLRP3 inflammasome activation has been implicated in various types of leukemia, including myelodysplastic syndrome, myeloproliferative neoplasms, AML, CML, and ALL." (PMID 39769450, 2024). "In the present study, we documented that primary AML leukemia cells over-expressed NLRP3 inflammasome associated molecules at the mRNA and protein levels which were correlated with poor risk of AML patients." (PMID 34211462, 2021). "They found increased expression of key components of the NALP3 pathway - CASP1 (encoding caspase 1) and its activator NLRP3 in GC-resistant leukemia cells compared to GC-sensitive leukemia cells." (PMID 33747919, 2021). "Here, we discuss both roles shown in murine and human studies and introduce new insights for the effect of oncogenic mutations in inducing NLRP3 inflammasome activation in leukemias." (PMID 32733479, 2020). "Furthermore, NLRP3 inflammasome and caspase-1 activation have been associated with glucocorticoid resistance in leukemia cells, which has implications for treatment response and disease recurrence." (PMID 39769450, 2024). "We found that NLRP3 inflammasome caused a worse outcome and more leukemia infiltration." (PMID 34211462, 2021). "For example, NLRP3 participates in the development and expansion of HSPCs, and their release from bone marrow into the peripheral blood has been implicated in certain hematological disorders including various types of leukemia." (PMID 34769275, 2021). "For example, NLRP3 participates in the development and expansion of HSPCs and their release from bone marrow (BM) into the peripheral blood and has been implicated in certain hematological disorders including various types of leukemia." (PMID 34769275, 2021). "Furthermore, to explore the endogenous deficiency of NLRP3 in AML, we knocked down NLRP3 in leukemia cells by using siRNA transfection." (PMID 34211462, 2021). "In addition, activation of the NLRP3 inflammasome causes glucocorticoid resistance in leukemia cells by cleavage of the glucocorticoid receptor and decreased promoter methylation of caspase-1 and NLRP3." (PMID 30937316, 2019). "As for malignancies of lymphoid origin, CASP1 and NLRP3 showed significantly higher expression in glucocorticoid-resistant primary leukemia cells from patients diagnosed with acute lymphoblastic (ALL) compared to cells sensitive to glucocorticoids." (PMID 38397043, 2024). "Taken together, these findings show that NLRP3 is a critical driver of leukemia development and AML progression in vivo." (PMID 39223663, 2024). "Current findings on ALL indicate that glucocorticoid resistance, linked to poorer prognosis, correlates with elevated caspsase-1 and NLRP3 expression, due to reduced methylation of their promoters in leukemia cells." (PMID 39769450, 2024). "As shown by microscopy, leukemia cells infiltration in spleen and bone marrow showed alleviated tendency in NLRP3-/- mice compared with those in control AML mice." (PMID 34211462, 2021). "Although leukemia is an inflammation-driven cancer, the effect of NLRP3 inhibitors on this disease has hardly been investigated yet." (PMID 33525345, 2021). "Meanwhile, CASP1 and its activator NLRP3 are the core component of the inflammasome, and its overexpression in leukemia leads to glucocorticoid resistance." (PMID 33999861, 2021).
leukemia (continued). "Then, we co-cultured NLRP3-activated THP-1 cells with primary leukemia cells using Transwell chamber." (PMID 34211462, 2021). "Even though NLRP3 is the best-studied member of the inflammasome family, its specific roles in leukemia remain contentious." (PMID 33525345, 2021). "Then, we designed two groups of C57BL/6J AML mice, one for injection with NLRP3-/- AML leukemia cells and one for injection control AML leukemia cells." (PMID 34211462, 2021). "In AML murine model, up-regulation of NLRP3 increases the leukemia burden in bone marrow, spleen and liver, and shortens the survival time; furthermore, knocking out NLRP3 inhibits leukemia progression." (PMID 34211462, 2021). "In this review, we summarize the current knowledge on leukemia-promoting inflammation and, in particular, the role of the NLRP3 inflammasome in different types of leukemia." (PMID 33525345, 2021). "To clarify this effect, we firstly activated the NLRP3 inflammasome using LPS in primary AML leukemia cells." (PMID 34211462, 2021). "The activation of NLRP3 inflammasome in AML cells promotes leukemia cells proliferation, inhibits apoptosis and increases resistance to chemotherapy, while inactivation of NLRP3 by caspase-1 or NF-κB inhibitor shows leukemia-suppressing effects." (PMID 34211462, 2021). "Since leukemia is known to be an inflammation-driven cancer and IL-1β is produced in elevated levels by leukemic cells, research on NLRP3 in the context of leukemia has increased in recent years." (PMID 33525345, 2021). "In this study, in primary AML leukemia cells, LPS or LPS+ATP induced NLRP3 inflammasome activation and the activation of NLRP3 inflammasome promoted proliferation, inhibited apoptosis and increased drug-resistance of primary leukemia cells." (PMID 34211462, 2021). "The functions of the NLRP3 inflammasome in leukemogenesis of the different leukemia types are very distinct; it can both promote and, also, inhibit the emergence and progression of cancer." (PMID 33525345, 2021). "This link was recognized previously, but the crosstalk between NLRP3 and autophagy in the context of leukemia is poorly understood." (PMID 33525345, 2021). "Our results showed that the culture medium of NLRP3-activated THP-1 cells inhibited primary leukemia cells apoptosis, and the inhibitory effect had partially reversed after neutralization with anti-IL-1β, while anti-IL-18 had no this effect." (PMID 34211462, 2021). "Oncogenic KRAS leads to ROS production, NLRP3 activation and consecutive release of IL-1β in a myeloid leukemia mouse model, and KRAS-mutant human leukemia cells exhibit increased NLRP3 inflammasome activation." (PMID 34064909, 2021). "The studies described so far have all reported that NLRP3 is upregulated in different types of leukemia and has a tumor-promoting effect through different mechanisms." (PMID 33525345, 2021). "We have recently reported a novel function of the NLRP3 inflammasome in the pathogenesis of hematological malignancies, particularly myeloproliferation in leukemias." (PMID 32733479, 2020). "The Nlrp3 inflammasome is also involved in certain hematological pathologies, including (i) myelodysplastic syndrome, (ii) myeloproliferative neoplasms, (iii) leukemia, and (iv) graft-versus-host disease (GvHD) after transplantation." (PMID 32313108, 2020). "This process plays an important role in the pathogenesis of the leukemia seen in elderly patients as a consequence of inflammaging, which is driven, at least partially, by activation of the Nlrp3 inflammasome." (PMID 32313108, 2020). "This initial triggering step leading to NLRP3 inflammasome activation has been widely assessed using in vitro assays based on the human monomyelocytic leukemia cell line, THP-1." (PMID 30943996, 2019). "The requirement for the NLRP3 protein in inflammasome activation has so far only been shown in mouse macrophages and a human leukemia-derived THP-1 cell line." (PMID 29153837, 2017).
leukemia (continued). "Contrary to P2X7R, present data show that NLRP3 is down-modulated in leukemia cells and negatively correlates with proliferation." (PMID 27221966, 2016). "Notably, in contrast to the other 23 cancer types in the PPTC study, pediatric leukemia emerges with significantly higher NLRP3 expression." (PMID 40104043, 2025). "Thus, recent studies suggest that the NLRP3 inflammasome-mediated immune and inflammatory responses play a significant role in leukemia, contributing to disease progression, drug resistance, and therapy response." (PMID 39769450, 2024). "All these findings suggested that the higher expression and activity of NLRP3 inflammasome in bone marrow leukemia cells may play a vital role in AML." (PMID 34211462, 2021). "Therefore, this review discusses chronic inflammation and the NLRP3 inflammasome in the context of leukemia and its preforms and briefly summarizes the current knowledge about their interrelationships." (PMID 33525345, 2021). "Furthermore, inhibition of NLRP3 inflammasome activation manifests anti-leukemia effects both in vitro and in vivo." (PMID 34211462, 2021). "All these findings illustrate the evidence that highly activated NLRP3 inflammasome in AML bone marrow leukemia cells correlates with poor prognosis and may act through IL-1β pathway in AML." (PMID 34211462, 2021). "In fact, NLRP3 has been shown to be differently regulated in several tumors from leukemia (increased), thyroid carcinoma (increased), lymphoid neoplasm diffuse large B cell Lymphoma (decreased), thymoma (decreased), and uterine carcinosarcoma (no changes), to mention a few." (PMID 33649199, 2021). "Furthermore a functional link between KRASG12D mutation and NLRP3 activation by the KRAS/RAC1/ROS/NLRP3 axis has been demonstrated both in KRAS mutant murine bone marrow (BM) and in leukemia human cells." (PMID 33429941, 2021). "Moreover, we upregulated NLRP3 expression by lentivirus transfection in leukemia cells to study its effect on drug resistance." (PMID 34211462, 2021). "Additionally, we up-regulated the expression of NLRP3 in the murine leukemia cell line C1498 by lentivirus." (PMID 34211462, 2021). "Single-cell suspensions from spleen, liver or bone marrow were determined using flow cytometry analysis, and the results showed that the percentages of GFP+ leukemia cells in these organs from NLRP3-GFP AML mice were significantly higher than those from Ctrl-GFP AML mice." (PMID 34211462, 2021). "Compared with the controls, the end of network for AML patients was pointed from IL-1β to IL-1R and from NLRP3 to NF-κB, which indicates that NLRP3 inflammasome may act through IL-1β or NF-κB in AML leukemia cells." (PMID 34211462, 2021). "Furthermore, we explored the role of NLRP3 inflammasome activation in AML chemotherapy, and found that the killing effect of ADR or DNR on leukemia cells was reversed by LPS-induced NLRP3 activation." (PMID 34211462, 2021). "Leukemia cells in bone marrow or liver were examined by microscopy, and we observed that liver and bone marrow sections showed more leukemia cells infiltration in NLRP3-GFP AML mice compared with control mice." (PMID 34211462, 2021). "Furthermore, we have recently reported that the use of MCC950 in KrasG12D-mutant leukemia mouse models improves myeloproliferation and cytopenia phenotypes, by attenuating NLRP3 inflammasome." (PMID 32733479, 2020). "Up to now, NLRP3 inflammasome research was limited to macrophages and especially to mouse bone marrow-derived or human peripheral blood mononuclear cell-derived macrophages or human leukemia cell line THP-1." (PMID 31892810, 2019). "Inspired by a recent article showing that steroid-resistance in leukemia cells is caused by caspase-1-dependent cleavage of the GR30, we hypothesized that the activation of the NLRP3 inflammasome in THP-1 cells could lead to a reduction of GR levels." (PMID 27883019, 2016).